ARID1A (AT-rich interaction domain 1A)
Diseases named in the same sentence as ARID1A in open-access papers (continued):
Sharing a sentence is not in itself a finding about the gene and the disease.
colon carcinoma (50 papers, 2012 to 2025). "Many solid tumors have mutations in SWI/SNF that cause PRC2 hyperactivity; for example, colon cancer cells can have ARID1A and SMARCA4 driver mutations." (PMID 41000734, 2025). "ARID1A is also frequently misregulated in colon cancer, so we made use of a CRISPR-Cas9 knockout (KO) mutation of ARID1A in the HCT116 colon cancer cell line." (PMID 40938753, 2025). "ARID1A mutations can lead to cancer phenotypes as shown with colon cancer in mice, which suggests a tumor suppressive function of ARID1A." (PMID 38587186, 2024). "Of note, ARID1A acts as a tumor suppressor gene in colon cancer and loss-of-function mutations are found in approx. 10% of the cases, often in association with the MSI-high status." (PMID 39246444, 2024). "In KRAS-mutated colon cancer, a similar tumor-supporting role of ARID1A was required for MEK/ERK signaling." (PMID 38310130, 2024). "mutations in ARID1A impair enhancer-mediated gene regulation and prognosis in patients with colon cancer." (PMID 36238278, 2022). "ARID1A mutations was found correlated with markedly higher level of immune infiltrates in colon cancer." (PMID 36238278, 2022). "Here, colon cancer and colon development‐associated gene sets were particularly abundant in the ARID1A upregulated group." (PMID 36420658, 2022). "In colon cancer, ARID1A protein loss was associated with clinicopathologic features, distant metastases, and poor overall survival." (PMID 34414106, 2021). "In colon cancer, ARID1A-deficient cells exhibit reduced expression of topoisomerase 2A and a decatenation defect, which render tumor cells sensitive to an ATR serine/threonine kinase inhibitor or PARP inhibitor." (PMID 31238554, 2019). "ARID1A (missense) mutations are found in patients with colon cancer, and ARID1A loss promotes invasive adenocarcinoma via SWI/SNF-dependent gene expression regulation in vivo or proliferation/5-fluorouracil (5-FU) resistance in vitro." (PMID 31238554, 2019). "In a mouse model of colon cancer, based on the conditional deletion of Arid1a, loss of ARID1A correlated with reduced binding of SWI/SNF at enhancers and reduced expression of cognate genes." (PMID 31123059, 2019). "Only few SWI/SNF components (BRM, BRG and ARID1A) have been reported mutated or deregulated in colon cancer; limited functional insights into the mechanisms of oncogenesis promoted by chromatin remodelling complexes are available so far." (PMID 24286138, 2013). "Moreover, ATAC-seq experiments conducted in colon cancer HCT116 cells proved that the loss of ARID1A profoundly altered chromatin accessibility, revealing a pivotal role of ARID1A in chromatin organization, determining a “gain or loss” of accessibility." (PMID 36890819, 2023). "Additionally, many other driver genes are frequently mutated in colon cancer, such as ARID1A, SOX9, FAM123B, BCL9L, RBM10, CTCF, and KLF5." (PMID 34912802, 2021). "ARID1A is frequently mutated in colon cancer, with nonsense and out-of-frame mutations." (PMID 33321074, 2021). "Accordingly, the screening strategy that targets multiple cancer types with a mutation in the same epigenetic regulator (for example, the ARID1A mutation in ovarian and colon tumors) may aid in the identification of therapeutics." (PMID 31238554, 2019). "Interestingly, another gene coding for a subunit of the SWI/SNF complex (ARID1A/BAF250A) has been found to have frameshift or nonsense mutations in up to 10% of colon tumors, suggesting that abnormalities in ARID1A protein may have a role colon carcinogenesis." (PMID 29894502, 2018). "Finally, ARID1A, a chromatin remodeling gene, has also been reported to be mutated in colon cancer." (PMID 26379039, 2015). "For example, in a mouse model of colon cancer with Apc inactivation, Arid1a is considered essential for tumorigenesis." (PMID 38835016, 2024).
colon carcinoma (continued). "For example, Arid1a-deficient CAR-T cell therapy markedly suppressed tumor growth in mouse colon cancer models while the use of Arid1a inhibitor in vivo decreased anti-tumor efficacy." (PMID 37398660, 2023). "According to our prior findings, ARID1A expression is decreased in colon cancer, which has a poor prognosis." (PMID 36420658, 2022). "We then examined VIM and ARID1A expression levels in ARID1A COAD tissues to assess ARID1A's correlation with colon cancer." (PMID 36420658, 2022). "Our study focused on the specific molecular mechanism of ARID1A in colon cancer proliferation and metastasis via VIM/CDH dysregulation." (PMID 36420658, 2022). "Radiosensitizing effect of ATRi (VE822) for ARID1A+ and ARID1A- colon cancer cell lines from the clonogenic assay." (PMID 36249060, 2022). "VIM and CDH1 appear to be ARID1A's molecular targets in colon cancer, which improve colon cancer cell viability, invasion and proliferation, especially in cells with ARID1A downregulation." (PMID 36420658, 2022). "Chip‐qPCR analysis showed that ARID1A binds to the promoters of both genes and changes their expression in colon cancer." (PMID 36420658, 2022). "Recent research has indicated that ARID1A plays a significant function in colon cancer cell proliferation and migration via CDH1 regulation." (PMID 36420658, 2022). "In this study, we investigated the ARID1A‐VIM/CDH1 signalling axis's role in colon cancer proliferation and migration." (PMID 36420658, 2022). "We also uncovered the prognosis significance of low ARID1A levels in colon cancer, using RNA sequencing data from the TCGA database." (PMID 34414106, 2021). "The results indicate that the ARID1A gene expression profile predicts recurrence and death in colon cancer patients." (PMID 34414106, 2021). "ARID1A shows a positive correlation with a wide range of chemokines and immune cell biomarkers, chemokines, receptors, and inhibitors in colon cancer." (PMID 34414106, 2021). "Similarly, in HCT116 (colon cancer cell) and OVCA429 (CCOC) cells, two additional ARID1AWT lines, loss of ARID1A protein by ARID1A CRISPR knockout led to increased sensitivity to BRD4i-DDRi combinations (P < 0.01, P < 0.001 respectively)." (PMID 37841875, 2023). "Besides, pre-treatment of naive CD8+ T cells with Arid1a inhibitor markedly promoted their effector function and increased anti-tumor efficacy in mouse melanoma and colon cancer models." (PMID 37398660, 2023). "The ARID1A subunit targets SWI/SNF complex to enhancers and loss of ARID1A impairs the enhancer-mediated transcriptional program of colonic epithelium and drives colon cancer in mice." (PMID 37548349, 2023). "Because EMT is a crucial step in colon cancer growth, invasion and metastasis, we searched for EMT‐associated genes in ARID1A knockdown cells and showed that ARID1A deficiency leads to EMT phenotype and affects the survival of COAD patients via targeting EMT genes." (PMID 36420658, 2022). "But simultaneous mutation of ARID1A and ARID1B is synthetically lethal for colon cancer." (PMID 36238278, 2022). "For the first time, we have found evidence of the ARID1A pathway influencing EMT in colon cancer." (PMID 36420658, 2022). "Silencing of ARID1A in gastric, ovarian, glioma, and colon cancer cells has been shown to activate the phosphorylation of AKT, and PI3K, suggesting an interrelationship between ARID1A deficiency and PI3K/AKT pathway activation." (PMID 35070505, 2022). "ARID1A significantly correlates with VIM in colon cancer (p = 0.0142, r = 0.45)." (PMID 36420658, 2022). "To address this gap, we searched for miRNAs-targeted ARID1A in TCGA-based data tools and found a subset of miRNAs that may target ARID1A in colon cancer." (PMID 34414106, 2021). "We further investigated the clinicopathological role of ARID1A expression in colon cancer." (PMID 34414106, 2021).
colon carcinoma (continued). "Also, a correlational analysis was presented based on TCGA colon cancer data between mRNA ARID1A expression and clinicopathological features, tumor-infiltrated immune cells, immune inhibitors, activators, and chemokines." (PMID 34414106, 2021). "Notably, ARID1A alterations were correlated with markedly high immune infiltrates in endometrial, stomach and colon cancer." (PMID 31949479, 2020). "In contrast to the general notion of ARID1A as a tumor suppressor, as demonstrated in the colon cancer model, deletion of Arid1a in mouse liver protected against development of HCC, suggesting that Arid1a is necessary for the initiation of tumorigenesis in hepatocytes." (PMID 31731480, 2019). "Variants in the ARID1A gene, which encodes a key component of the highly conserved SWI–SNF (switch/sucrose non-fermentable) chromatin remodeling complex, were identified in 18/37 colon cancer patients with 13 different variants." (PMID 29844865, 2018). "In conclusion, CRC cells with ARID1A silencing had higher levels of VIM and lower levels of CDH1 expression, which are both positively correlated with ARID1A in colon cancer tissues." (PMID 36420658, 2022). "qPCR was used to analyse ARID1A and EMT markers expression levels in colon cancer." (PMID 36420658, 2022). "However, the molecular mechanisms by which ARID1A is involved in colon cancer metastasis and primary tumorigenesis are not well understood." (PMID 36420658, 2022).
clear cell carcinoma (49 papers, 2012 to 2026). "SKOV3 has characteristics of clear cell adenocarcinomas with microsatellite instability and carries ARID1A and MLH1 mutations." (PMID 38798714, 2024). "Endometrioid and clear cell carcinoma each represent about 10% of ovarian tumors and have high rates of ARID1A mutations (30 and 50%, respectively) and PTEN alterations including deletions and mutations." (PMID 38352443, 2024). "Isolated alterations of the ARID1A gene are common in many differentiated epithelial carcinomas, especially in the gynecologic tract, where they are associated with clear cell carcinoma but also endometrioid and mucinous carcinoma." (PMID 37686505, 2023). "Endometrioid and clear cell carcinomas, frequently associated with endometriosis, are characterized by alterations of CTNNB1, PTEN, and POLE mutations, while clear cell carcinomas are characterized by ARID1A mutations." (PMID 35163166, 2022). "In line with our results, ARID1A mutations have previously been suggested as an interesting actionable alteration for PARPi therapy, especially in clear cell carcinomas." (PMID 33947352, 2021). "For endometrioid and clear cell carcinomas, almost all our patients with postulated PARPi sensitivity harbored ARID1A mutations." (PMID 33947352, 2021). "Endometrioid tumors are characterized by β-catenin alterations, microsatellite instability, and PTEN and POLE mutations, while ARID1A mutations occur in both endometrioid and clear cell carcinomas." (PMID 33919741, 2021). "A good amount of research was also done in terms of targeted therapy for AT-rich Interactive Domain 1A (ARID1A) mutated clear-cell carcinoma, such as ENMD-2076." (PMID 32679669, 2020). "On the other hand, most of clear cell carcinomas with ARID1A loss-of-function mutations showed a loss of ARID1A protein expression." (PMID 32868822, 2020). "In 2010, two groups almost simultaneously reported somatic ARID1A (AT-rich interactive domain 1A gene) mutations in 57% and 46% of clear cell carcinomas, respectively." (PMID 32023964, 2020). "For example, mutations of the ARID1A gene is associated with increased sensitivity to HDAC6 inhibition in clear cell carcinomas." (PMID 33322608, 2020). "ARID1A protein expression was observed in 9 of 56 clear cell carcinoma samples (16.1%) with ARID1A loss-of-function mutations." (PMID 32868822, 2020). "Of 60 clear cell carcinoma samples with ARID1A mutations, 49 (81.7%) showed a loss of ARID1A protein expression." (PMID 32868822, 2020). "On the other hand, our study demonstrated that ARID1A protein expression was retained in 16% of clear cell carcinomas harboring ARID1A loss-of-function mutations." (PMID 32868822, 2020). "In particular, clear cell carcinoma samples which harbor multiple ARID1A loss-of-function mutations or both a single ARID1A loss-of-function mutation and ARID1A allelic imbalance lost ARID1A protein expression." (PMID 32868822, 2020). "In particular, all clear cell carcinoma samples harboring both ARID1A loss-of-function mutations and ARID1A allelic imbalance showed a loss of ARID1A protein expression." (PMID 32868822, 2020). "ARID1A is a tumor suppressor gene mutated in ∼50% of ovarian endometrioid and clear cell carcinomas, as well as a significant percentage of the corresponding uterine tumors, resulting in loss of immunoexpression of its protein product, BAF250a." (PMID 30550483, 2019). "Mutations in the chromatin modulator ARID1A have been implicated in endometrioid ovarian cancers and clear cell carcinomas." (PMID 30646939, 2019). "The frequent mutations of ARID1A offered the opportunity to investigate the relationship existing between ovarian endometriosis and clear cell carcinoma." (PMID 29389895, 2018). "ID8 cells also lack other mutations typical of clear cell carcinoma (Arid1a, Pik3ca), low-grade serous carcinoma (Braf), endometrioid (Ctnnb1), or mucinous (Kras) carcinomas." (PMID 29927933, 2018).
clear cell carcinoma (continued). "The frequency of ARID1A mutations was higher than that in previous reports, especially for clear cell carcinoma." (PMID 29599905, 2018). "The JHOC-5 clear cell carcinoma cell line bears the tumor suppressor gene ARID1A (encoding BAF250) and PIK3CA mutations, which cooperate to promote tumor growth through IL-6 overproduction." (PMID 29930760, 2018). "Previous studies have shown that ovarian endometrioid and clear cell carcinomas express the similar genetic mutations, such ARID1A and PI3K." (PMID 28388560, 2017). "Preclinical studies suggest that targeting the PI3K-Akt pathway inhibits clear cell carcinoma tumor growth in a mouse model and that loss of ARID1A further sensitizes cells to PI3K- and Akt-inhibition." (PMID 27231561, 2015). "CTNNB1 (beta-catenin) mutations are common in endometrioid carcinomas, PICK3CA mutations are most frequent in clear cell carcinoma, and ARID1A (the AT-rich interactive domain 1A) mutations are often observed in both tumor types." (PMID 23319948, 2012). "It is reported that a nonsense or indel mutation of ARID1A was correlated with loss or reduction of protein expression in uterine endometrioid carcinoma, ovarian endometrioid carcinoma and clear cell carcinoma." (PMID 22808142, 2012). "On the other hand, clear cell carcinoma’s relatively better prognosis may be linked to its distinct molecular profile, characterized by frequent ARID1A and PIK3CA mutations, which could offer actionable therapeutic targets." (PMID 40095664, 2025). "In the majority of patients with endometrioid and clear cell carcinomas and potential actionability, ARID1A truncating or splice mutations were observed (7/11 and 9/11, respectively), whereas only one high-grade serous carcinoma patient harbored such a mutation (P = 0.001)." (PMID 33947352, 2021). "ARID1A (AT-rich interactive domain containing protein 1A) loss-of-function mutations have been reported in gynecological cancers, including rarer subtypes such as clear cell carcinoma." (PMID 34518240, 2021). "However, ARID1A protein expression was retained in seven clear cell carcinomas with ARID1A loss-of-function mutations." (PMID 32868822, 2020). "The presence of ARID1A loss-of-function mutations was significantly associated with the loss of ARID1A protein expression in clear cell carcinomas (P < 0.001) and the representative ARID1A staining images correspond to four patterns on the basis of ARID1A mutations and ARID1A protein expression." (PMID 32868822, 2020). "In addition to specific HDAC inhibitors, pan-HDAC inhibitors have shown significant activity against ARID1A-mutated tumors in preclinical models of clear cell carcinoma." (PMID 30646939, 2019). "Importantly, HNF1β expression and/or loss of ARID1A expression can indicate clear cell carcinoma." (PMID 38573494, 2024). "Because we could not use serial sections for both immunohistochemical analysis in this study and target gene sequencing in the previous study, we validated the ARID1A mutation status of FFPE tissue samples in nine clear cell carcinoma samples with ARID1A truncating mutations." (PMID 32868822, 2020). "A clear-cell carcinoma is associated with PIK3CA and ARID1A mutations, whereas endometrioid ovarian cancer is associated with mutations in CTNNB1, PTEN, and ARID1A mutations." (PMID 38541242, 2024). "Clear cell carcinomas were examined in 20.7% (n = 333) of the cases, with genomic alterations in ARID1A (n = 231, 69.4%) and PIK3CA (n = 190, 57.1%), consistent with previous reports." (PMID 38201563, 2023).